RN7SKP14 (RN7SK pseudogene 14)
Gene: Miscellaneous RNA gene on chromosome 17 (54,770,949 to 54,771,277, forward strand). Ensembl gene ENSG00000251809.
Homologues: Orthologues: chimpanzee 7SK (100% identical), guinea pig 7SK (40% identical). Paralogues in human: 7SK (60% identical), RN7SKP174 (59% identical), RN7SKP48 (59% identical), RN7SKP187 (58% identical), RN7SKP118 (57% identical), RN7SKP185 (57% identical), RN7SKP178 (56% identical), RN7SKP62 (56% identical), RN7SKP104 (55% identical), RN7SKP227 (55% identical), RN7SKP77 (55% identical), RN7SKP250 (54% identical), and 284 more.